HPN-AS1 (HPN antisense RNA 1)
Gene: Long non-coding RNA gene on chromosome 19 (35,027,447 to 35,106,898, reverse strand). Ensembl gene ENSG00000227392.
Diseases named in the same sentence as HPN-AS1 in open-access papers:
HPN-AS1 is named in the same sentence as 4 diseases in open-access papers, as found by Europe PMC text mining. Sharing a sentence is not in itself a finding about the gene and the disease. The quoted sentences say what the papers report.
breast carcinoma (1 paper, 2021). "MiR-200c-3p, miR-204-5p, miR-20b-5p, miR-7-1-3p, miR-105-5p, miR-342-3p, DNMBP-AS1, HPN-AS1, LINC00461, LINC00472, LINC00667, LOC100128164, LOC284578, MESTIT1, RHPN1-AS1, and SLC26A4-AS1 were significantly associated with breast cancer patients’ overall survival (log-rank P < 0.05)." (PMID 34220926, 2021).
HPN-AS1 also shares sentences with these, for which no sentence is quoted: cancer (1 paper); hepatocellular carcinoma (1); papillary thyroid carcinoma (1).